NBR1 (NBR1 autophagy cargo receptor)
Diseases named in the same sentence as NBR1 in open-access papers (continued):
Sharing a sentence is not in itself a finding about the gene and the disease.
muscular disease (1 paper, 2023). Myopathy is a peripheral nervous system disease consisting of any abnormal condition or disease of the muscular tissues; commonly designates a disorder involving skeletal muscle. "This review aims to summarize what has been studied so far about the direct involvement of aggrephagy and the activation of the key players, among others, p62, NBR1, Alfy, Tollip, Optineurin, TAX1BP1 and CCT2 in muscular diseases." (PMID 37176163, 2023).
Myeloma (1 paper, 2016). "HT-29 (Colon), MDA-MD-361 (Breast), MM1.S (Myeloma), and HCT116 (Colon) xenograft tumor models showed a high level signal of NBR1 and low level of LC3B." (PMID 27247826, 2016).
prostatitis (1 paper, 2025). An infectious or non-infectious inflammatory process affecting the prostate gland. "Our analysis revealed two Tier 2 genes (NOA1 and ELAC2) for BPH, two Tier 3 genes (TRMU and SFXN5) for prostatitis, and six Tier 3 genes (MRPL24, NDUFS6, PUS1, NBR1, GLOD4, and PCBD2) for PCa." (PMID 40919435, 2025). "We revealed two Tier 2 genes (NOA1 and ELAC2) and one Tier 3 gene (ACAT1) for BPH, two Tier 3 genes (TRMU and SFXN5) for prostatitis, and six Tier 3 genes (MRPL24, NDUFS6, PUS1, NBR1, GLOD4, and PCBD2) for PCa." (PMID 40919435, 2025).
pulmonary fibrosis (1 paper, 2024). Chronic progressive interstitial lung disorder characterized by the replacement of the lung tissue by connective tissue, leading to progressive dyspnea, respiratory failure, or right heart failure. "According to our study, protodioscin inhibits oxidative stress through the NBR1-p62-Nrf2 pathway and, as such, it exerts an anti-pulmonary fibrosis effect." (PMID 38589903, 2024). "Our results suggest that protodioscin is of therapeutical potential for treating pulmonary fibrosis, and, in this context, we suggest that the NBR1-p62-Nrf2 pathway represents a promising therapeutic target that can be further explored." (PMID 38589903, 2024). "The NBR1-p62-Nrf2 axis is targeted by protodioscin to reduce oxidative stress and inhibit pulmonary fibrosis." (PMID 38589903, 2024). "Significant associations between the levels of NRB1 and p62 were observed in IPF and control tissues, suggesting involvment of NBR1 in lung fibrosis through p62." (PMID 38589903, 2024). "This suggests that NBR1-p62-Nrf2 is a key target for the anti-oxidative stress effect of protodioscin and its anti-pulmonary fibrosis effect and may also serve as novel but promising drug target for treating pulmonary fibrosis." (PMID 38589903, 2024). "Moreover, from a clinical perspective, targeting the NBR1-p62-Nrf2 pathway could potentially lead to the development of innovative therapeutic strategies for managing pulmonary fibrosis, addressing a critical medical need." (PMID 38589903, 2024).
renal tumour (1 paper, 2018). "We collected 10 renal tumour samples with characteristic eosinophilic cytoplasmic inclusions (ECIs) and found that the ECIs were majorly composed of sequestosome 1/P62, neighbor of BRCA1 gene 1 (NBR1), PEX14, and CATALASE1 (CAT1)." (PMID 29967346, 2018).
respiratory failure (1 paper, 2007). The significant impairment of gas exchange within the lungs resulting in hypoxia, hypercarbia, or both, to the extent that organ tissue perfusion is severely compromised. "The importance of the titin–Nbr1–p62–MuRF-2 interaction is underlined by a human mutation disrupting binding of Nbr1 to titin, which causes an autosomal dominant muscle disease called heredity myopathy with early respiratory failure (HMERF)." (PMID 18047744, 2007).
skin cancer (1 paper, 2024). "UVB radiation downregulates METTL14 protein expression through NBR1 autophagy cargo receptor (NBR1)-dependent selective autophagy, further reducing global genome repair (GGR) and translation of DDB2 transcripts and inducing the development of skin cancer." (PMID 38473842, 2024).
steatosis (1 paper, 2024). Increased lipid within the cytoplasm of cells. "The HFD induced steatosis, along with a 2.4-fold increase in pexophagy receptor NBR1-positive granules in hepatocytes." (PMID 39765694, 2024). "Clofibrate significantly inhibited HFD-induced steatosis, increasing p62-, LAMP2-, and Pex5-positive granules by 7.5-, 7.2-, and 71.4-fold, respectively, while decreasing NBR1 expression." (PMID 39765694, 2024).
tuberous sclerosis (1 paper, 2017). Hereditary disease characterized by seizures, intellectual disability, developmental delay, and skin and ocular lesions. "It was recently shown that the overexpression of PEX3 induces ubiquitination-dependent NBR1-mediated pexophagy and that PEX19 associates with the tuberous sclerosis complex, which is part of the signaling cascade downstream of ATM activating pexophagy in the presence of ROS." (PMID 28817674, 2017).
urothelial carcinoma (1 paper, 2023). A malignant neoplasm derived from the transitional epithelium of the urinary tract (urinary bladder, ureter, urethra, or renal pelvis). "The authors also showed that knocking out the NBR1 gene potentiated rapamycin-induced inhibition of cell growth and proliferation in urothelial carcinoma cells." (PMID 36642223, 2023).
urothelial carcinoma of the bladder (1 paper, 2023). "In an in vitro study of urothelial carcinoma of the bladder involving treatment with rapamycin, the NBR1 gene was also found to be upregulated, and in the same report, clinical samples linked upregulation of NBR1 with higher recurrence of the disease." (PMID 36642223, 2023).
tumor (29 papers, 2011 to 2025). "Given the significant connection between MHC-I and antigen presentation, vital for the anti-tumor activity of immune cells, intervening with NBR1 emerges as a potential avenue to modulate autophagy." (PMID 40422248, 2025). "Based on the expression level of NBR1 in tumor cells, tumor tissues were divided into high and low expression groups of NBR1, and the exhaustion scores of CD8+ T cells were calculated for each group." (PMID 40373256, 2025). "Our study mainly focused on that OASL facilitates the degradation of MHC-I and slack of anti-tumor adaptive immunity derived from CD8+T cells through NBR1-mediated autophagy-lysosomal degradation." (PMID 39990208, 2025). "LINC01592 from M2 MDEs directly interacts with E2F6 in tumor cells, facilitating its nuclear translocation and boosting the transcription of NBR1." (PMID 40612677, 2025). "M2 TAMs-derived exosomes contain LINC01592, which can be transported into tumor cells and subsequently facilitate tumor growth by inhibiting the E2F6/NBR1/MHC-I signaling pathway." (PMID 40607254, 2025). "Mice implanted with RM-1 cells with simultaneous USP8 knockdown and NBR1 overexpression showed higher tumor growth rates compared with those bearing USP8-silencing cells." (PMID 40410130, 2025). "Another analogous study suggests that LINC01592 secreted by M2-TAMs binds to E2F6 in tumor cells, enhancing NBR1 transcription, leading to MHC-I degradation and defective anti-tumor immunity." (PMID 39223632, 2024). "The siRNA or antibody blockade of LINC01592/E2F6/NBR1/MHC-I greatly diminished LINC01592's tumor-supporting effects and suppressed M2-dependent tumor growth." (PMID 37915049, 2023). "In this investigation, it was demonstrated that the origin of LINC01592 from M2-TAM exosomes enhanced evasion of the immune system by the tumor through the activation of E2F6/NBR1/MHC-I signaling pathway." (PMID 37915049, 2023). "Disruption of LINC01232/E2F2/NBR1/MHC‐I by shRNA or blocking the corresponding antibodies largely diminished the tumor‐supportive effects of LINC01232 and suppressed tumor growth driven by M2‐type macrophages." (PMID 37097629, 2023). "Disruption of E2F2/NBR1/MHC‐I signaling by shRNA or blockade of the corresponding antibodies largely abolished the tumor‐supportive effects of LINC01232 and inhibited tumor growth driven by M2‐type macrophages." (PMID 37097629, 2023). "Disruption of E2F2/NBR1/MHC‐I signaling with shRNAs or blockade with the corresponding antibodies largely abolishes the tumor‐supportive effects of LINC01232 and inhibits tumor growth driven by M2‐type macrophages." (PMID 37097629, 2023). "A nude mouse intracranial orthotopic tumor model was established as follows: Vector/LINC01232‐OE/LINC01232‐OE+ NBR1‐KD U‐87MG/U‐251 cells were orthotopically implanted into the mouse brain." (PMID 37097629, 2023). "Selective autophagy cargo receptor neighbor of BRCA1 (NBR1) acts a key factor of autophagy-mediated focal adhesion turnover, thereby enhancing tumor migration." (PMID 36831455, 2023). "The tumor-promoting effects of LINC01592 were significantly reduced through the disruption of E2F6/NBR1/MHC-I signal axis." (PMID 37915049, 2023). "Even in autophagy-competent cells, the ectopic overexpression of NBR1 was sufficient to promote tumor metastasis." (PMID 36255390, 2022). "Injection of tumor cells overexpressing NBR1 led to metastatic outgrowth, while overexpression of p62 did not." (PMID 36255390, 2022). "Together, all these antecedents strongly indicate that distribution of MHC-I at the cell surface is controlled by NBR1 selective autophagy, highlighting NBR1 as a crucial molecule in how tumor cells evade the immune system." (PMID 33634029, 2020). "For example, Gambogic acid (GA), an anti-tumor drug and ROS inducer, cleaves and inactivates both p62 and Nbr1, among others, through ROS-mediated caspase activation." (PMID 30250843, 2018).
tumor (continued). "A panel of xenograft tumors was analyzed for LC3B and NBR1 using the Amp HQ method, as a way to assess the variability of basal autophagy activity across various tumor types." (PMID 27247826, 2016). "Using the Amp HQ method on Calu-6 xenograft sections, both LC3B and NBR1 were clearly detected as dark-staining puncta structures in the cytoplasm of viable tumor." (PMID 27247826, 2016). "By doing so, it influences the expression of MHC-I, suggesting that autophagy could promote tumor progression through an immune mechanism by intervening with NBR1." (PMID 40422248, 2025). "NBR1 also participates in the regulation of cancer cell migration, a process tightly controlled by focal adhesions (FAs), which are protein complexes that anchor tumor cells to the extracellular matrix (ECM) via integrins." (PMID 39596452, 2024). "Moreover, in comparison with others autophagy genes, NBR1 expression is found increased in intrahepatic cholangiocarcinoma tumor samples compared to normal controls." (PMID 33634029, 2020). "For example, it is known that NBR1 contributes for cancer cell migration, a process finely regulated by structures called focal adhesions (FAs), a large protein complex that connects tumor cells with the extracellular matrix (ECM) through the action of integrins." (PMID 33634029, 2020). "The data showed a wide range of basal LC3B and NBR1 signals across the various tumor models." (PMID 27247826, 2016). "Interestingly, the results of cell coculture showed that LINC01232‐OE/U‐87MG/U‐251 cells significantly inhibited T‐cell‐mediated tumor cell killing compared with vector; however, knocking down NBR1 while overexpressing LINC01232 could reverse this phenomenon." (PMID 37097629, 2023). "Our study demonstrated that OASL-knockdown increased MHC-I levels by inhibiting NBR1-mediated autophagy-lysosomal degradation in PDAC, contributing to the infiltration of CD8+T cells and tumor suppression." (PMID 39990208, 2025). "NBR1 then binds to ubiquitinated MHC‐I, facilitating its degradation in autophagolysosomes, enabling tumour cells to evade CD8+ T cell attack." (PMID 40673641, 2025). "We found that the elevated MHC-I levels on tumor cells surface after knocking out circGRAMD4, RBM4, and NBR1 decreased again with the knockout of B2M, and the corresponding changes in cancer cell death and CD8+ T cytokine levels also occurred." (PMID 40373256, 2025). "Then we conducted rescue experiments on tumor cells that had knocked out circGRAMD4, RBM4 and NBR1 by knocking out B2M again to reduce the expression level of MHC-I on the cell surface." (PMID 40373256, 2025). "As anticipated, immunohistochemistry staining of PDX tumor tissues showed that treatment with si-circGRAMD4 resulted in reduced levels of MKI67/Ki67, LC3B, and NBR1 proteins, while increasing MHC-I protein levels." (PMID 40373256, 2025). "In this regard, they observed that NBR1, a crucial autophagosome content receptor in solid tumors, plays a central role in the expression of MHC-I on the surface of the tumor cells, as well as within autophagosomes and lysosomes." (PMID 40422248, 2025). "However, other studies suggest that NBR1 might have tumor-promoting properties." (PMID 39596452, 2024). "Under autophagy-lysosome signaling, NBR1 promotes the ubiquitination-mediated degradation of MHC-I, impairing anti-tumor immunity." (PMID 39223632, 2024). "The tumor-promoting impacts of LINC01592, as well as the growth of M2-type macrophage-driven tumors, were significantly suppressed by the interruption of E2F6/NBR1/MHC-I signaling through the effect of siRNA or the corresponding antibody blockade." (PMID 37915049, 2023). "In this study, we found that TAMs secrete exosomes rich in LINC01232 into tumor cells and that LINC01232 directly binds E2F2 and promotes E2F2 entry into the nucleus; the two synergistically promote the transcription of NBR1." (PMID 37097629, 2023).
tumor (continued). "In these tumor cells, knockdown of the autophagy cargo receptor gene, NBR1, increased MHC-I surface expression, confirming the implication of NBR1-mediated autophagy-lysosomal pathway in the process." (PMID 33335860, 2020). "U87 MG (Brain) and SKOV-3 (Ovary) xenograft tumor models showed a high level signal of LC3B and low level of NBR1." (PMID 27247826, 2016). "In oesophageal cancer, the LINC01592/E2F6/NBR1/MHC‐I axis enhances MHC‐I degradation in autophagolysosomes and reduces its surface expression on cancer cells, facilitating immune evasion by CD8+ CTLs and promoting tumour progression." (PMID 40673641, 2025). "We tested this hypothesis by establishing a B16‐EGFP tumor‐bearing model using normal B16‐EGFP cells, Rbfox3 knockout B16‐EGFP cells, or Nbr1 knockout B16‐EGFP cells." (PMID 39777898, 2025). "This increases the binding of NBR1 to ubiquitinated MHC-I proteins through its ubiquitin-binding domain, increasing degradation of MHC-I in autolysosomes and reducing MHC-I surface expression on tumor cells." (PMID 40612677, 2025). "In addition, through TCGA database analysis, we found that NBR1 and E2F2 are highly expressed in tumor tissues, and the expression of E2F2 was inversely proportional to patient prognosis, consistent with our previous results." (PMID 37097629, 2023). "Intriguingly, the accumulation of NBR1, but not p62, promoted the development of an aggressive subpopulation of tumor cells." (PMID 36255390, 2022). "Conversely, NBR1 induces MHC-I selective autophagic degradation in PDAC consequent tumor immune escape, while autophagy inhibitor treatment increases the efficiency of anti-tumor immune therapy." (PMID 34493296, 2021). "Compared with normal tissues, tumor tissues showed significantly higher mRNA levels of the following key autophagy genes: ATG5, ATG7, ATG3, ATG9A, ATG9B, ATG12, AMBRA1, and NBR1." (PMID 32582551, 2020). "The other four genes (CPS1, COL12A1, EIF3H, and NBR1) were not upregulated in the tumour region of MSSCC." (PMID 21847129, 2011). "Furthermore, deletion of receptor‐interacting protein kinase 2 (RIPK2), a key regulator of the tumour microenvironment, disrupts NBR1‐mediated degradation and further augments MHC‐I surface expression, ultimately sensitizing PDAC tumours to anti–PD‐1 immunotherapy." (PMID 40673641, 2025). "LINC01232 binds to E2F2 to enter the nucleus and collaboratively upregulates NBR1, mediating the degradation of histocompatibility complex Class I molecules (MHC-I) by autophagy lysosomes, enabling CD8+ T cells to effectively recognize tumor-specific antigens and thereby evade immune surveillance." (PMID 40585979, 2025). "It has been shown that the upregulated hub MMRG genes BCL2, MAVS, FKBP8, NBR1, and SLC25A6 and their products can participate in regulating drug resistance of tumour cells and the antitumour immune response and may be associated with the activation of inflammatory signalling pathways." (PMID 41463291, 2025). "It was found that the exosome LINC01232 antigen from M2-type TAMs promoted the transcription of NBR1 by binding to E2F2, and NBR1 binds to MHC-I protein, mediating the increased degradation of MHC-I in the autophagolysosome, eventually decreased the expression of MHC-I on the surface of tumor cells." (PMID 39654892, 2024). "Furthermore, testing for possible anti-tumor effects of copper (I) nicotinate complex (CNC) on squamous cell cancer revealed that the drug could decrease general autophagy levels and elevate Nbr1 expression through yet unknown mechanisms." (PMID 30250843, 2018). "The results of IF analysis of Ki‐67 in the transplanted tumor specimens from the animals indicated that mice in the sh‐1232#1 group expressed less Ki‐67 than mice in the sh‐NC group; next, LINC01232 knockdown and simultaneous overexpression of NBR1 could reverse this phenomenon." (PMID 37097629, 2023).
tumor (continued). "The results of IHC analysis of CD8+ in tumor specimens transplanted into the animals demonstrated that, compared with mice in the sh‐NC group, those in the sh‐1232#1 group obviously expressed more CD8+; next, LINC01232 knockdown with simultaneous overexpression of NBR1 could reverse this phenomenon." (PMID 37097629, 2023). "The IHC results of CD8+ in animal transplanted tumor specimens demonstrated that, compared with mice in the vector group, those in the LINC01232‐OE group had significantly lower expression of CD8+; next, NBR1 knockdown with simultaneous LINC01232 overexpression could reverse this phenomenon." (PMID 37097629, 2023). "The IF results of Ki‐67 in the transplanted tumor specimens from the animals indicated that mice in the LINC01232‐OE group had increased expression of Ki‐67 compared with the mice in the vector group; next, NBR1 knockdown with simultaneous overexpression of LINC01232 could reverse this phenomenon." (PMID 37097629, 2023).